BMAL1 (basic helix-loop-helix ARNT like 1)
Diseases named in the same sentence as BMAL1 in open-access papers (continued):
Sharing a sentence is not in itself a finding about the gene and the disease.
cancer (continued). "NAMPT thus is a target of both BMAL1:CLOCK and oncogenic MYC in Myc-driven cancers." (PMID 28674522, 2017). "Also, our further study on HeLa cancer cells showed consistent results that PIWIL2 suppresses the interaction between GSK3β and BMAL1, leading to the failure of ubiquitination and degradation of the latter protein." (PMID 28903391, 2017). "Furthermore, genomic integrity may be compromised due to the influence of CLOCK, BMAL1, PER, and CRY on key signaling pathways such as c-Myc/p21 and Wnt/β-catenin, potentially leading to impaired DNA damage responses in cancer." (PMID 40700255, 2025). "However, circadian disruption is not universally observed in cancer cells, and BMAL1 depletion improves outcomes in some cancer models." (PMID 39070610, 2024). "In addition, there is a strong connection between Bmal1 and Per2 regulation and the PI3K/mTOR signaling pathway, one of the most frequently activated signaling pathways in tumorigenesis and the progression of cancer." (PMID 36768253, 2023). "CLOCK -BMAL1 and MYC-MAX both have very similar heterodimer structures and bind to largely identical promoter sequences, setting up the possibility that these two transcription factor heterodimers have overlapping functions and may compete in cancer cells." (PMID 34299381, 2021). "Furthermore, long-term observations of animals with single or double deletions of clock genes such as Per1,2−/− and Cry1,2−/− or mice lacking a single copy of Bmal1, revealed them to be cancer-prone." (PMID 28425940, 2017). "It remains to be determined in what contexts overexpressed MYC in cancer deregulates clock genes through either promoter co-occupancy, competition with CLOCK-BMAL1 to trasactivate or repress target genes, or through forming novel complexes with either CLOCK or BMAL1." (PMID 27500134, 2016). "Another study identified CSNK1e (protein CK1ε) as a synthetic lethal target of MYC and N-MYC upregulated in neuroblastoma and other human cancers, and upregulation of CK1ε would be expected to destabilize the clock through its promotion of PER degradation and activation of BMAL1." (PMID 27500134, 2016). "Unlike CLOCK, BMAL1 has been reported as having oncostatic effects in cancer development." (PMID 26220712, 2015). "In addition, the majority of malignant pleural mesothelioma (MPM) cell lines, and a subset of MPM clinical specimens, expressed more BMAL1 compared to their non-cancer controls (non-tumorigenic mesothelial cell line - MeT-5A - and normal parietal pleura, respectively)." (PMID 32388500, 2020). "However, the mechanism of BMAL1 in the development of various cancers is not fully understood." (PMID 31346317, 2019). "Indeed, the effectors of the core clock machinery might also display non-circadian functions, which would be involved in the cancer development, as exemplified by BMAL1 function during early development." (PMID 28674522, 2017). "In cancer models where MYC is upregulated (by another oncogene or through circadian disruption), and is still circadian-controlled, MYC does not seem to exert a strong effect in suppressing BMAL1 and ablating rhythmicity of the molecular clock or downstream targets." (PMID 37639465, 2023). "Hence, we speculate that the lower expression of PER1 in cancer cells can influence the activation and the intracellular distribution of CLOCK/BMAL1, rather than the alteration in expression level." (PMID 27602964, 2016).
metabolic disorders (34 papers, 2011 to 2026). "The disruption of circadian rhythms (CRs) has been linked to metabolic disorders, yet the role of hepatic BMAL1, a key circadian regulator, in the whole-body metabolism and the associated lipid metabolic phenotype in the liver remains unclear." (PMID 38892255, 2024). "The deficiency of the RRE-mediated rhythmic transcription of Bmal1 might result in a pathological condition similar to chronic inflammation and metabolic disorders, possibly due to the phase-delayed profile of the gene expression." (PMID 35999195, 2022). "However, the ClockΔ19 mutant combines with Bmal1 to form a dimer and cause a rhythm disorder, resulting in a more pronounced metabolic disorder in ClockΔ19 mice than in Clock knockout mice." (PMID 29283886, 2017). "Given the role IL-1β plays in perpetuating chronic inflammation in metabolic disorders and that circadian disruption further enhances susceptibility to these disorders, our findings may identify BMAL1 as a critical regulator of this glucose metabolism-inflammation feedback loop." (PMID 34858390, 2021). "With CR disorder being recognized in metabolic diseases, BMAL1 has attracted increasing attention, and animals with global or conditional knockout of BMAL1 are ideal models for metabolism investigation." (PMID 38892255, 2024). "BMAL1 also governs adipogenesis, and circadian disruption impacts lipid metabolism, leading to metabolic disorders in early life." (PMID 38553412, 2024). "Tissue-specific deletion of Bmal1 in the liver, pancreas, adipocytes, skeletal muscle, and intestines recapitulates the discrete elements of metabolic disorders under various environmental stimuli." (PMID 37299510, 2023). "Disruption of BMAL1 function leads to dysregulation of lipid metabolism and metabolic disease, indicating the potential role of BMAL1 in accelerated aging." (PMID 35733785, 2022). "HFD reduced the expression of Bmal1/Clock transcription complex at the mRNA level, indicating the link between the circadian clock and metabolic disorders." (PMID 31408938, 2019). "Moreover, targeted regulation of HIF1α/BMAL1 are potential nutritional approach in reducing metabolic disorders in various mammary gland disorders in dairy animals." (PMID 40307878, 2025). "Furthermore, disruption of BMAL1 function in visceral adipose tissue is observed in patients with metabolic diseases." (PMID 38553412, 2024). "BMAL1 is one of the clock genes and is related to tumors, metabolic diseases, aging, etc.." (PMID 36975874, 2023). "BMAL1 impairment results in protein catabolism in muscle, reduced disposal of amino acids in the liver, and increased blood plasma amino acids, which couples the metabolism disorder with aging." (PMID 35733785, 2022). "Given that NFκB activation may contribute to metabolic disease and aging in part through dysregulation of BMAL1 circadian systems, further study can take NFκB into consideration as a plausible target for therapeutic repression in anti-aging." (PMID 35733785, 2022). "Circadian rhythm disorders (CRD) affect the expression levels of circadian rhythms-associated genes in brain and muscle aryl hydrocarbon receptor nuclear translocator-like-1(BMAL1), which is thought to contribute to metabolic disorders and an altered immune system." (PMID 36613816, 2022). "Altogether, intestine clock functions as an accelerator in dietary fat absorption and targeting intestinal BMAL1 may be a promising approach for management of metabolic diseases induced by excess fat intake." (PMID 34493722, 2021). "Importantly, it has been pointed out in the literature that the clock gene Bmal1 has crucial effect on macrophages in a variety of diseases, such as inflammatory and metabolic diseases." (PMID 33790796, 2021). "Thus, given that class 3 PI3K is ubiquitously expressed, its functional interaction with Bmal1 for purine metabolism might expand beyond the liver into other organs and could be relevant in metabolic diseases." (PMID 37414850, 2023).
metabolic disorders (continued). "However, TRF/E may contribute to the prevention of metabolic diseases via modulation of the Clock–Bmal1 pathway, synchronizing hormonal signals, regulating the Sirt1 pathway, inhibiting mTOR signaling, and modulating gut-microbiome-related nutrient-sensors." (PMID 36678130, 2023). "Therefore, we propose that intestine clock functions as an accelerator in dietary fat absorption and targeting intestinal BMAL1 may be a promising approach for management of metabolic diseases induced by excess fat intake." (PMID 34493722, 2021). "Second, BMAL1 KO in mice causes circadian arrhythmicity, sleep and metabolic disorders, and premature aging, and a non-human primate model could be useful for multiple disease areas in supplement of deficiencies found in Bmal1 mice." (PMID 34691834, 2019). "In our study, the expression of both per2 and per3 were decreased in the WD group, and the expression of Bmal1 was increased, which may lead to disruption of circadian clock and metabolic disorder, and the disturbed expression of per2, per3 and Bmal1 were all rescued by fish oil feeding." (PMID 26832365, 2016). "Liver clock genes BMAL1 and PER2 are similarly reduced in animal models for both PCOS and NAFLD, emphasizing the commonality between these metabolic disorders." (PMID 39858445, 2025). "Therefore, BBR might be an effective natural compound for alleviating redox homeostasis, metabolism disorder, and liver pathological changes in MAFLD by activating Clock and Bmal1 expression." (PMID 36838862, 2023).
infection (32 papers, 2015 to 2026). The state of being infected such as from the introduction of a foreign agent such as serum, vaccine, antigenic substance or organism. "For viral infections, transgenic mice models deficient for BMAL1 displayed greater viral replications after infection with murid herpes or influenza viruses." (PMID 35890319, 2022). "While certain immune cells and related factors normally exhibit diurnal patterns over 24-h, Bmal1 deficiency specifically from myeloid cells or neutrophils abolishes their rhythmic trafficking and impairing the host’s ability to clear infection." (PMID 33255707, 2020). "For example, global Bmal1 deficient mice are more susceptible to infection and selective Bmal1 deletion from ILCs results in reduced ILC cellularity in the intestine." (PMID 33255707, 2020). "Recently, it has been reported that infection cycles of flaviviruses and some associated immune response genes are subject to circadian rhythm influences controlled by the circadian clock genes BMAL1 and REV-ERBα." (PMID 32722523, 2020). "Bmal1 deficiency in bone marrow-derived macrophages leads to increased IL-1β expression and increases polymicrobial infection in mice." (PMID 33363534, 2020). "Importantly, pp containing either spike variants showed reduced infection of Bmal1-silenced Calu-3 cells." (PMID 34545347, 2021). "Bmal1 is best known for its role in circadian regulation and has been shown to control rhythmic monocyte recruitment, which plays a key role in the immune response against pathogens and in limiting infection-associated inflammatory damage." (PMID 32396064, 2020). "In addition to impacting infection clearance ability, loss of Bmal1 only in monocytes also induces a significant increase in weight gain when given high-fat diet (HFD) compared to wild-type (WT) controls." (PMID 33255707, 2020). "Deletion of Bmal1 in primary Bmal1fl/fl neuron cultures via infection with an AAV8-Cre viral vector (versus AAV8-eGFP control) suppressed the BMAL1 transcriptional target Nr1d1 (which encodes REV-ERBα) by 85% and induced C4b expression but caused no increase in C3." (PMID 33258449, 2020). "We identify the antiviral transcription factor IRF1 as a direct target of the circadian transcription factor BMAL1, resulting in rhythmic expression of a basal antiviral gene program prior to infection." (PMID 42182353, 2026). "The core protein BMAL1 is thought to be essential for coordinating clock output and metabolic adaptation, playing a vital defense against infection, ROS accumulation, and oxidative damage." (PMID 39442875, 2025). "In cells with normal expression of the Bmal1 gene, infection with ZIKV at 2 dpi significantly decreased claudin-5 mRNA levels." (PMID 40313764, 2025). "In pigs infected with the PRRSV, BMAL1 helps modulate the circadian rhythms of macrophages and neutrophils, ensuring that the innate immune response is properly synchronized to combat the infection." (PMID 40284797, 2025). "Briefly, brain endothelial cells cultured on 6-well plates were transfected with Bmal1 siRNA, following infection with ZIKV at MOI 0.01." (PMID 40313764, 2025). "Remarkably, CCM significantly suppressed most genes within this panel, indicating a gain of BMAL1 anti-infection function." (PMID 40133642, 2025). "We found that treatment with the circadian-enhancing agents nobiletin and SR8278 reduced infection of herpes simplex virus 1 in epidermal explants and human keratinocytes in a BMAL1/CLOCK-dependent manner." (PMID 37725438, 2023). "This time-of-day effect on outcome is likely to be mediated via the molecular oscillator as abolishing circadian rhythmicity by knocking out BMAL1 increased viral protein expression, markers of infection and pulmonary damage." (PMID 37314017, 2023). "Remarkably, diurnal rhythms of Ly6Chi depend on BMAL1, and are necessary for a proficient immune response to infection." (PMID 32232012, 2020).
infection (continued). "With the infection of Mycobacterium tuberculosis, the level of BMAL1 was significantly decreased in both the lung and the spleen." (PMID 33042871, 2020). "We determined the circadian period length of the primary fibroblast cells by lentiviral infection with a construct expressing a luciferase gene under the control of a BMAL1 promoter." (PMID 29930532, 2018). "That said, within 2 days of infection mean activity was actually higher in BMAL1 KO mice during the light phase, suggesting a brief period of diurnal preference following IAV infection." (PMID 25923474, 2015). "The body weight of WT and BMAL1 KO IAV infected mice dropped by day 2 post-infection and remained low until day 8 post-infection when compared to control mice of both strains." (PMID 25923474, 2015). "Both BMAL1 KO and WT mice showed significant reductions in daily activity on days 1–9 post-infection." (PMID 25923474, 2015). "Further, to more directly assess the role of the timing system in response to infection, we measured activity, body weight, mortality, inflammation and emphysematous responses in the lungs of BMAL1 knockout mice and WT littermates following IAV infection." (PMID 25923474, 2015). "BMAL1 KO-Virus infected mice showed increased mortality beginning 5 days post-infection and by day 9 all of the BMAL1 KO mice infected with IAV was deceased." (PMID 25923474, 2015). "The authors of this study postulated that the seasonality in BMAL1 levels may contribute to the fact that infections with viruses such as influenza are more common in winter." (PMID 35890319, 2022). "Taken together, we report a gain in macrophage function following deletion of the core clock protein BMAL1, and reveal a mechanism in which BMAL1 acts as a repressor of the immune system, operating as a “brake,” regulating the magnitude of phagocytosis responses following infection." (PMID 31900362, 2020). "An implication from our current studies, and yet to be tested, is that following infection, enhanced phagocytosis may also be mediated by a similar rapid degradation of BMAL1 protein in macrophage cells." (PMID 31900362, 2020). "Similarly, viral infections are enhanced in Bmal1−/− mice, while the magnitude of infection by distinct protozoan parasites, including Plasmodium and Leishmania major also presents significant variation along the day, or even in response to time of feeding." (PMID 32232012, 2020). "To investigate the role of the molecular clock in the response to IAV infection, we measured lung compliance, resistance and tissue elastance in WT mice infected with IAV on day 9 post-infection, uninfected BMAL1 heterozygous KO mice and uninfected homozygous BMAL1 KO mice." (PMID 25923474, 2015). "However, we were unable to evaluate immune cells in lungs of infected BMAL1 KO mice due to 100% mortality in this group by day-9 post-infection." (PMID 25923474, 2015). "Conversely, some studies showed a certain promoting effect of BMAL1 on gastric epithelial cells with the infection of Helicobacter pylori, which could be attributed to the various roles of BMAL1 in different diseases or the various types of bacteria executing infections in different conditions." (PMID 33042871, 2020). "Since endogenous BMAL1 mRNA levels, promoter of which drives luciferase in this study, were comparable between the proliferative and senescent cells, the high luciferase intensity could be due to high infection efficiency in the senescent cells." (PMID 30738414, 2019). "In this study, we found that the expression level of main piRNA-generation genes BMAL1 and CRY1 were significantly downregulated after SVA infection, which indicated that SVA infection did have an effect on circadian rhythm in PK-15." (PMID 37323834, 2023). "In contrast, targeting the macrophage by knocking out BMAL1 using two different cre drivers (LYSM and CX3CR1) abolished the time-of-day phenotype protecting mice from infection and reducing inflammation." (PMID 37314017, 2023).
infection (continued). "To assess the impact of BMAL1 on SARS-CoV-2pp entry, we infected the silenced Calu-3 cells and showed a significant reduction in pp infection, whereas VSV-Gpp infection was unaffected." (PMID 34545347, 2021). "The time of infection impacted late-viral clearance and IAV survival in Bmal1fl/fl Ercre+ mice, and this time-of-day observed variation was abolished in Bmal1−/− mice." (PMID 32012758, 2020). "Locomotor activity of BMAL1 KO and WT littermates was monitored before (5 days) and after IAV infection (1–9 days post-infection)." (PMID 25923474, 2015). "In addition, we found that the expression levels of the major piRNA-generating genes BMAL1 and CRY1 were significantly downregulated after SVA infection." (PMID 37323834, 2023). "BMAL1 KO mice infected with IAV also displayed a significant decline in body weight and survival (100% mortality), suggesting that proper function of the timing system is necessary for maintaining the innate immune response to infection." (PMID 25923474, 2015). "BMAL1 KO-Saline treated mice displayed a significant increase in lung compliance and decrease in resistance and elastance when compared to WT-Virus infected mice suggesting an inherent defect in the lung mechanical properties of BMAL1 KO mice in the absence of infection." (PMID 25923474, 2015). "Furthermore, SARS-CoV-2pp infection was significantly reduced by SR9009 treatment in parental Calu-3 cells but not in shBmal1 silenced cells, demonstrating a BMAL1 dependency." (PMID 34545347, 2021).